PALB2 (partner and localizer of BRCA2)
Diseases named in the same sentence as PALB2 in open-access papers (continued):
Sharing a sentence is not in itself a finding about the gene and the disease.
breast cancer (continued). "BRCA1-associated breast cancers tended to be earlier onset at diagnosis (p = 0.003), and when invasive, were higher grade (p < 0.001), node-negative (p = 0.01), and more commonly TNBC (%TNBC: 69.4% BRCA1 vs. 24.7% BRCA2 vs. 31.6% PALB2; p < 0.001)." (PMID 40275390, 2025). "Interestingly, for PALB2, the risk of CBC was increased if the primary breast cancer was ER-negative (HR 2.9; 95% CI 1.4–6.4; p = 0.006), whereas it was increased for CHEK2 if the primary breast cancer was ER-positive (HR 2.0; 95% CI 1.1–3.5; p = 0.02)." (PMID 39858629, 2025). "In our study, PALB2 was associated with a 37% likelihood of bilateral mastectomy at index breast cancer surgery, but this did not account for women undergoing risk reducing surgery during follow-up." (PMID 40275390, 2025). "In summary, postmenopausal carriers of PVs in BRCA1/2, ATM, CHEK2, and PALB2 are unlikely to have substantial (twofold or greater) elevations in the risk of developing breast cancer due to reproductive and lifestyle exposures." (PMID 40298171, 2025). "For both PALB2 and CHEK2, a high PRS was associated with an increased risk of breast cancer." (PMID 40227593, 2025). "The results suggested that annual MRI screening from 30 to 35 years, followed by annual mammography at 40 years, might reduce breast cancer mortality by over 50% for women with ATM, CHEK2, and PALB2 P/LP variants." (PMID 39858629, 2025). "This has led to recommendations from multiple studies, including the American Society of Breast Surgeons, for broader genetic testing, encompassing BRCA1/2, PALB2, and other appropriate genes based on the clinical picture, for all patients with a history of breast cancer." (PMID 40941615, 2025). "Another study indicated that the estimated lifetime breast cancer risk for BRCA1 and BRCA2 PV carriers increased with higher PRS313 scores, though the observed effect was smaller than in the general population or among carriers of PVs in ATM, CHEK2, and PALB2." (PMID 40296163, 2025). "Deficiencies in the DNA damage repair pathway related genes constitute an important factor in the development of breast cancer, with approximately 10% of breast cancer cases being caused by mutations in HR genes, such as BRCA1, BRCA2, PALB2, BRIP1, BARD1, and RAD51C." (PMID 40830526, 2025). "BRCA1/2, ATM, CHEK2, and PALB2 PV carriers do not have breast cancer OR ≥2.0 with many established risk factors." (PMID 40298171, 2025). "When β1 is large, β2>12β1, as is observed for BRCA1, BRCA2 and PALB2 for breast cancer." (PMID 39749474, 2025). "Even for those tested during adulthood, the robust recall of an individual with a GPV in, for example, PALB2 at 25–30 years for breast cancer surveillance, then again at 50 years of age regarding ovarian cancer risk management, requires careful coordination with inbuilt failsafes." (PMID 41159931, 2025). "Chemotherapy receipt is high in BRCA1/2 and PALB2-associated breast cancers including in early stage, node-negative disease." (PMID 40275390, 2025). "Approximately 72% of BRCA1 carriers and 22–34% of BRCA2 and PALB2 carriers diagnosed with breast cancer present with triple-negative breast cancer (TNBC) a particularly aggressive biologic subtype that almost always necessitates chemotherapy even if tumors are small at diagnosis." (PMID 40275390, 2025). "The recommended surveillance is based on current UKCGG guidelines, including an anticipated change in guidance, implemented in April 2025, recommending that all individuals with a GPV in BRCA1/BRCA2/PALB2 are eligible for enhanced breast cancer surveillance from the age of 25 years." (PMID 41159931, 2025).
breast cancer (continued). "Expanding access to genetic testing and availability of validated breast cancer (BC) risk prediction models are increasingly identifying women at elevated BC risk who do not carry high-penetrance BRCA1/BRCA2/PALB2 pathogenic variants." (PMID 40705362, 2025). "DNAJA3 was significantly coexpressed with PALB2 in breast cancer." (PMID 39468330, 2024). "The present study pioneered the acquisition of the mutational landscape of the breast cancer susceptibility genes (ATM, CHEK2, PALB2, and XRCC2) using next-generation whole-exome sequencing from paraffin-fixed FFPE tissue blocks obtained from the breast cancer patients of Pashtun ethnicity." (PMID 38784039, 2024). "Besides, two of the 12 (16.7%) PALB2 carriers were diagnosed with mixed invasive micropapillary carcinoma, an aggressive type of breast cancer with an unfavorable clinical prognosis." (PMID 38914840, 2024). "Considering breast cancer-associated mutations across a broader range of genes (BRCA1, BRCA2, PALB2, and the more moderate-risk genes, ATM and CHEK2), the average carrier risk is equivalent to the top 3% of the PRS distribution (see S1 File for definition of mutation carriers)." (PMID 39292644, 2024). "Besides, rare variants in other genes like ATM, CHEK2, CDH1, PALB2, RAD50, and RAD51C have been detected mainly in the breast cancer subgroup." (PMID 39148954, 2024). "This suggests that the occurrence of LGRs in PALB2 among Asian breast cancer patients may be very rare." (PMID 38914840, 2024). "Among the genes known to play a relevant role in mammary tumors, BRCA1 (BReast CAncer gene 1) and PALB2 (Partner And Localizer of BRCA2), two breast cancer susceptibility genes whose mutations result in familial cases of the disease, seem to be required for RARα signaling." (PMID 38360674, 2024). "Patients with PALB2 pathogenic variants were more likely to have a positive family history of breast cancer and/or ovarian cancer than non-carriers (16.7% vs. 6.3%)." (PMID 38914840, 2024). "Therefore, our team used second-generation sequencing to detect whole-exon susceptibility gene mutations and mutations in four breast cancer susceptibility genes (BRCA1, BRCA2, PALB2, and RECQL) in Chinese women." (PMID 38439896, 2024). "In the RADIOLA study, the RAD51-foci score is investigated if it has a predictive value on Olaparib efficacy in g/sBRCA or PALB2 or RAD51C/D mutation carrier advanced breast cancer patients; no results were posted." (PMID 38540206, 2024). "This study aimed to assess the spectrum and clinicopathological features of PALB2 pathogenic variants in Chinese patients with early-onset breast cancer, irrespective of family history." (PMID 38914840, 2024). "Individuals with a pathogenic variant in BRCA1, BRCA2, or PALB2 had a risk of breast cancer well above 20% at age 70, regardless of their PRS or family history." (PMID 39669587, 2024). "Mutation spectrum of ATM, CHEK2, PALB2, and XRCC2 genes in patients with breast cancer." (PMID 38784039, 2024). "Both the ATM, PALB2 and CHEK2 genes are breast cancer susceptibility genes of moderate penetrance." (PMID 38504328, 2024). "An alternative approach (strategy #2) could entail discontinuing the ascertainment of family history of breast cancer and instead refer all women with a pathogenic variant in BRCA1, BRCA2, PALB2, ATM, and CHEK2 or a PRS in the top 10%." (PMID 39669587, 2024). "In summary, the prevalence of germline pathogenic PALB2 variants was approximately 0.77% in Chinese patients with BRCA1/2-negative early-onset breast cancer patients, irrespective of family history." (PMID 38914840, 2024).
breast cancer (continued). "In this genetic association study of 4121 patients with cancer and 5631 healthy controls, protein-truncating variants in the 5 major genes for breast cancer, particularly BRCA1/2 and PALB2 variants, were significantly associated with the occurrence of interval cancer." (PMID 38270937, 2024). "Carriers of PALB2 mutations have a four times higher risk of breast cancer than those without, and those with PALB2 mutations have a 14 and 35% risk of developing breast cancer at ages 50 and 70 years, respectively." (PMID 38439896, 2024). "We found that P/LP variants in the PALB2 gene are associated, although not significantly, with the risk of breast cancer (OR = 3.0)." (PMID 39684352, 2024). "Sensitivity analyses of the association between BRCA1/2 (and PALB2) variants and breast cancer in women without a strong family history yielded consistent estimates." (PMID 38270937, 2024). "According to a Korean BRCA1/2 negative breast cancer cohort study, it was confirmed that 2.43% (17/700) of BRCA1/2 negative breast cancers were caused by PALB2 variants." (PMID 39409938, 2024). "Although recent cohort studies suggest a possible survival benefit for prophylactic mastectomy in unaffected BRCA1 carriers, there are no data to suggest a survival benefit relative to MRI surveillance in unaffected BRCA2/PALB2 carriers or carriers with a prior history of breast cancer." (PMID 38248108, 2024). "While DVs of ATM, CHEK2, and PALB2 have been linked to breast cancer, the additional risk conferred is not as well understood, especially among individuals with non-European ancestries." (PMID 38760335, 2024). "As to genes other than BRCA1 and PALB2 that may be involved in the anti-proliferative action exerted by ATRA in mammary tumors, important clues come from gene-expression and DNA-methylation studies." (PMID 38360674, 2024). "Pathogenic variants (PVs) in BRCA1, BRCA2, PALB2, RAD51C, RAD51D, and BRIP1 cancer susceptibility genes (CSGs) confer an increased ovarian cancer (OC) risk, with BRCA1, BRCA2, PALB2, RAD51C, and RAD51D PVs also conferring an elevated breast cancer (BC) risk." (PMID 38334999, 2024). "The estimated lifetime risk of acquiring breast cancer with an ATM, CHEK2, PALB2 mutation is greater than 20% which is considered a “moderate risk” compared to the effects of the pathogenic variants in BRCA1 and BRCA2 genes with a lifetime risk of approximately 50%." (PMID 37239898, 2023). "Recent studies demonstrated that PARP inhibitor is effective in treating breast cancer patients carrying PALB2 PV or LPV, opening a new avenue of target treatment that might benefit breast cancer patients." (PMID 37169825, 2023). "We observed six known pathogenic or likely pathogenic variants, such as a frameshift variant in PALB2 (p.Leu531fs; AF of 0.1%, not observed outside Finland in gnomAD) associated with breast cancer." (PMID 36653562, 2023). "Pathogenic variants detected in other breast cancer susceptibility genes, such as ATM, CHEK2, PALB2, RAD51, and BARD, may also explain a proportion of the genetic risk." (PMID 37239898, 2023). "As expected by the global frequency, other non-BRCA genes related to hereditary breast cancer variants were found (PALB2 and CHEK2)." (PMID 36833268, 2023). "In our cohort, the odds ratio for breast cancer risk in women with PALB2 P/LP variants was between 8.1 and 9.3 compared to non-HBOC cancer patients and the non-cancer population, respectively." (PMID 37686625, 2023). "The quantitative assessment of the PALB2 gene as a potential marker could be considered anon-invasive method for breast cancer in the processes of prognostic evaluations, screening, andtreatment monitoring." (PMID 39430039, 2023). "We assessed the frequency of PALB2 variants in two breast cancer cohorts and a non-HBOC cancer patient cohort." (PMID 37686625, 2023).
breast cancer (continued). "Whole-exome sequencing data from 98 BRCA1/BRCA2/PALB2 founder mutation-negative Northern Finnish breast cancer cases with indications of hereditary disease susceptibility was used for the identification of rare CNVs." (PMID 37578974, 2023). "Twenty-one breast cancer (1.4%) and one non-breast cancer patient (0.17%) carried pathogenic/likely pathogenic PALB2 variants." (PMID 37686625, 2023). "While early age at diagnosis was strongly associated with BRCA1 and modestly with BRCA2, it was associated with only a very modestly (ATM and CHEK2) or no (PALB2) increased risk of carrying a PV in non-BRCA1/2 breast cancer-associated genes." (PMID 37084156, 2023). "In our cohort, the OR for breast cancer risk in women with PALB2 P/LP variants was between 8.1 and 9.3 compared to non-HBOC cancer patients and the non-cancer population, respectively." (PMID 37686625, 2023). "In addition to BRCA1 and BCRA2 genes, other genes, such as CHEK2, PALB2, and PTEN, are less common but also confer an elevated risk of breast cancer among men." (PMID 38146568, 2023). "In patients who are found not to carry a founder mutation, we perform full sequencing using gene panels including BRCA1, BRCA2, CHEK2, and PALB2 in breast cancer cases with familial clustering of this cancer and/or in patients with early onset disease (diagnosed at age 45 or below)." (PMID 37510234, 2023). "Moreover, next-generation sequencing revealed that beyond BRCA1/2, mutations in homologous recombination effectors, such as PALB2, RAD51, ATM, BRIP1, BARD1, and CHEK2 also occur in breast cancer." (PMID 36613148, 2023). "This study evaluated the effect of age at breast cancer diagnosis and cancer family history on the risk of carrying a PV in breast cancer susceptibility genes routinely included in breast cancer predisposition multi-gene panels, ATM, BRCA1, BRCA2, CHEK2, and PALB2." (PMID 37084156, 2023). "Unaffected women with familial breast cancer were about 2-times more likely to carry a PV in one of the high-penetrance breast cancer-risk genes (BRCA1, BRCA2, PALB2) compared to those with no familial breast cancer." (PMID 37084156, 2023). "This is in line with findings in moderate breast cancer risk genes such as CHEK2, PALB2 and ATM and suggests that PRS inclusion in risk stratification may in particular be relevant to prevent excess of surveillance measures in PV carriers of those genes." (PMID 36872334, 2023). "Frequency of PALB2 PV/LPV in breast cancer seems to be lower than in other population." (PMID 37169825, 2023). "For women with other HOC mutations associated with significant breast cancer risk such as CHEK2, PALB2 and ATM, the impact of RRBSO on breast cancer risk remains unknown." (PMID 35159349, 2022). "The aim of the study is to compare the outcomes of implant and synthetic TIGR mesh-based breast reconstructions in breast cancer patients and women, who have higher lifetime risk for breast cancer, with mutated (changed) copy of genes: BRCA1, BRCA2, PALB2 or CHEK2." (PMID 35804960, 2022). "In addition, more frequent, but less penetrant germline mutations have been identified in families with breast cancer in genes such as CHEK2, ATM, PALB2, and BRIP1." (PMID 35333900, 2022). "Women receive broad cancer risk figures that are not personalised (e.g., 44–63% lifetime risk of breast cancer for those with PALB2)." (PMID 35681696, 2022). "In addition, high expression of PALB2 predicts poor prognosis in patients with advanced breast cancer." (PMID 35779338, 2022). "Notably, only 6/19 (32%) of Palb2-CKO mice developed mammary tumors, likely due to a mostly C57BL/6 genetic background, which is known to be more resistant to mammary tumorigenesis." (PMID 35404932, 2022). "Currently, approximately 40% of familial breast cancer risk is explained by a combination of common low-penetrance variants, together with coding rarer variants in predisposition genes, such as BRCA1, BRCA2, PALB2, ATM, and CHEK2 that confer higher risks." (PMID 35884425, 2022).
breast cancer (continued). "Studies in breast cancer have shown that small samples (n = 3) with germline nonsense/frameshift variants in PALB2 have exhibited elevated Signature 3 activity." (PMID 36230674, 2022). "PALB2 mutation analysis in 94 breast cancer patients without BRCA1/2 mutations who had a family or personal history of PC showed a prevalence of 2.1%." (PMID 35761384, 2022). "PALB2 could be tested in families with recurring breast cancer or pancreatic cancers or in families with aggregation of MBC." (PMID 35454911, 2022). "However, other contributing factors for this association need to be investigated such as defects in homologous recombination (e.g., BRCA1, BRCA2, PALB2, ATM, CHEK2) known to increase risk of breast cancer." (PMID 36421330, 2022). "Reversion mutations within multiple genes in the HRR pathway, including BRCA1, BRCA2, RAD51C, RAD51D, and PALB2, have been reported in ovarian, prostate, and breast carcinomas as a mechanism of acquired or primary resistance to platinum-based chemotherapy and PARP inhibitors 7-18." (PMID 35281878, 2022). "In contrast, TNBC versus other tumor subtype was not more frequent among EA breast cancer cases with pathogenic variants in BRCA2 or PALB2 than among EA cases with no such variants (OR = 0.62 [0.18, 2.09])." (PMID 33479248, 2021). "Currently, there is no standardized therapy for PALB2 mutation associated breast cancer due to the limited amount of evidence available; however, some clinical trials have proved the use of PARP inhibitors as beneficial." (PMID 34439348, 2021). "Patients with the PALB2 mutation were most likely to have personal breast cancer only and no family history of prostate and ovarian cancer when comparing with BRCA1 carriers." (PMID 34439348, 2021). "We then investigated other breast cancer subtypes and whether they were also enriched in heterozygotes for a PALB2 PGV." (PMID 34113003, 2021). "Furthermore, PALB2 is the most frequently altered gene (1.2%) in non BRCA1/2 mutated male breast cancer patients, accordingly the risk of MBC increases from 9.63 to 17.30-fold in presence of PALB2 pathogenetic variants." (PMID 33718150, 2021). "In Haiti, 6.7% (5 of 75) of patients with breast cancer had a variant in BRCA1, BRCA2, or PALB2." (PMID 33646313, 2021). "We found evidence of association with breast cancer risk for four genes, with estimated adjusted ORs of 5.3 [95% CI: 2.1–16.2] for BRCA1, 4.0 [95% CI: 1.9–9.1] for BRCA2, 3.4 [95% CI: 1.4–8.4] for ATM and 4.3 [95% CI: 1.0–17.0] for PALB2." (PMID 34887416, 2021). "We next determined the power of the competing RVAS tests to identify the 8 breast cancer risk genes (BRCA1-Missense, BRCA1-LoF, BRCA2-Missense, BRCA2-LoF, PALB2, BRIP1, CHEK2 and BARD1) at the three TIER levels 5%, 0.1% and 0.01% and at three levels of VE of 2%, 1% and 0.5% (Iberian: S6 Fig)." (PMID 33606672, 2021). "Notably, individuals with PALB2 PVs more frequently had a triple-negative status (30%) vs. a frequency ranging between 12 and 17% in unselected patients with breast cancer." (PMID 33718150, 2021). "Similarly, a PALB2 screening study performed in 1403 female Australian breast cancer patients followed by screening of 779 families revealed that PALB2 c.3113G>A was the most recurrent familial mutation." (PMID 34439348, 2021).